STAT1 (signal transducer and activator of transcription 1)
Diseases named in the same sentence as STAT1 in open-access papers (continued):
Sharing a sentence is not in itself a finding about the gene and the disease.
influenza (continued). "In contrast to STAT1−/− NK cells, STAT4−/− NK cells were defective for IFN-γ production, but displayed WT levels of granzyme B induction following influenza infection." (PMID 23300570, 2012). "STAT1 was dispensable for IFN-mediated LATS1 phosphorylation and suppression of tissue repair, although as expected STAT1 was required for IFN-mediated protection from rhinovirus or influenza infection." (PMID 41587178, 2026). "Decreased expression of the IFN response genes Stat1, CXCL9, and CXCL10 may be due to suppression of the JAK/Stat signaling pathways in response to empagliflozin treatment during influenza infection." (PMID 38112660, 2023). "Therefore, we performed experiments in vitro by combining splenocytes (CD45.2+) from 129/Sv WT or STAT1−/− mice with those from B6 (CD45.1+) mice, followed by influenza infection." (PMID 23300570, 2012). "Influenza infection enhanced the expression levels of STAT1, phospho-STAT1, and MxA in A549 cells in the presence or absence of meth." (PMID 23139774, 2012). "The expression of interferon response genes STAT1, STAT2, Mx1, OASL2, ISG15, chemokines CCL2, CCL3, CXCL9 and CXCL10, and the frequency of neutrophils (CD45+CD11b+Ly6G+) and CD4+ T cells (CD45+CD4+) were all significantly increased in influenza-infected mice when compared to vehicle controls." (PMID 38750107, 2024). "These cases revealed the indispensable role of human intrinsic (TLR3, IRF7, IRF9, STAT1, and STAT2 in RECs, in which the virus replicates) and innate (IRF7 in plasmacytoid dendritic cells, in which the virus does not replicate) type I and III IFN immunity in host defense against influenza." (PMID 36112363, 2022). "Also, we recently identified that Type 17 immunity is rescued in the absence of STAT1 signaling during influenza-bacterial super-infection." (PMID 30337919, 2018). "In summary, influenza infection induced IL-27 production in an IFNAR-dependent pathway, which suppressed innate IL-17A production by γδ T cells upon secondary pneumococcal infection in a STAT1-dependent manner, thereby promoting the development of secondary pneumococcal pneumonia." (PMID 24408967, 2014). "In influenza patients, the interferon pathway-related genes IFI44, IFI6, IFIH1, STAT1, and GBP1 also showed overexpression, while no obvious interferon transcriptional signature was observed in AECOPD and CAP." (PMID 36059536, 2022). "By contrast, in their classifiers to distinguish bacterial infections from influenza or between different bacterial infections, practically no IFN regulated genes were found and only Stat1 overlapped with our blood signature." (PMID 21731757, 2011). "STAT1 and the JAK/STAT signaling pathway is known to be targeted by influenza virus, but IRF2 and IRF5 have not been demonstrated to play a role in response to influenza infection previously and thus represent novel predictions for further experimental investigation." (PMID 22074594, 2011).
leukemia (44 papers, 2013 to 2025). A malignant (clonal) hematologic disorder, involving hematopoietic stem cells and characterized by the presence of primitive or atypical myeloid or lymphoid cells in the bone marrow and the blood. "STAT1 has been reported to be a promoter of leukemia development and STAT1 deficient mice have been shown to be partially protected from leukemia development." (PMID 37928520, 2023). "Gene-profiling experiments showed that treating human leukemia HL-60 cells with Dip G was associated with a remarkable upregulation of STAT1 target gene expression, including IFIT3 and CXCL10." (PMID 28471454, 2017). "JAK2 tyrosine kinase and STAT1 both are highly associated with leukemia." (PMID 39113054, 2024). "Previous studies have reported that Stat1 activation enhances bcl2 expression and promotes leukemia." (PMID 39929806, 2025). "Although STAT1 has already been associated with a tumor suppressor role, typically linked to IFN-γ signaling, Kovacic (2006) proposes that STAT1 acts as a tumor promoter in the development of leukemia." (PMID 39272999, 2024). "Their results showed that STAT1−/− mice with leukemia exhibited low MHC type I expression to facilitate natural killer cell lysis for tumor clearance." (PMID 38675812, 2024). "Further experiments using CCRF-CEM and MOLT-3 T-ALL leukemia cell lines, corroborated upregulation of STAT-1 and L1CAM after treatment with NKG2D-CAR T cells." (PMID 37928520, 2023). "The activation of STAT1 has been confirmed in the differentiation of various drug-induced leukemia cells." (PMID 31117333, 2019). "The activation of signal transducer and activator of transcription 1 (STAT1) has a vital role in the terminal differentiation of immature leukemia cells." (PMID 28471454, 2017). "In a mouse model of v-abl-induced leukemia, Stat1-/- mice were partially protected from the development of leukemia, demonstrating that Stat1 possesses tumor-promoting activity." (PMID 27690235, 2016). "So far, our data demonstrate that caspase-mediated STAT1 cleavage exclusively occurs in leukemia cell lines." (PMID 24810717, 2014). "STAT1 is overexpressed or constitutively activated in some types of leukemia and this can correlate with a bad prognosis for the patients." (PMID 24810717, 2014). "Whereas butyrate reduces STAT1 in leukemia cells, most solid tumor-derived cells show an induction of STAT1 after treatment." (PMID 24810717, 2014). "Phospho-STAT1 was significantly decreased in all leukemia groups as compared to normal CD34+ samples." (PMID 25568664, 2014). "STAT1 activation was first identified in ATRA-induced myeloid differentiation of various leukemia cell lines." (PMID 23825585, 2013). "Furthermore, RIG-I activates the STAT1 molecule, to inhibit the proliferation ability of leukaemia cells." (PMID 39322862, 2024). "The presence of STAT1, recognized for its involvement in cellular stress and inflammation responses, added another layer of complexity, with contrasting views on its role as a tumor suppressor or promoter in leukemia development." (PMID 39272999, 2024). "For instance, STAT1 has been shown to facilitate the development of leukemia." (PMID 37968576, 2023). "Moreover, Stat1, the key effector of the IFNβ signal, was found to play a tumour promoter role in some cases of carcinoma, lymphoma and leukaemia." (PMID 32872349, 2020). "In sharp contrast, STAT1 was shown to be an immune tumor promoter for leukemia development." (PMID 32641473, 2020). "Furthermore, we found strong activation of Hif1α, Stat1 and Stat4 pathways in Gr-1+ population upon DS-5272 treatment, indicating the enhanced inflammatory signaling in the relatively differentiated leukemia cells in agreement with the RNA-seq data above." (PMID 31653912, 2019).
leukemia (continued). "Recently, we showed that also in ECs and VSMCs cross-talk between IFNγ and TLR4 resulted in augmented STAT1 phosphorylation and increased expression of the chemokine CXCL10 and the adhesion molecule ICAM-1 as well as adhesion of U937 leukemia cells to ECs, in a STAT1- and TLR4-dependent manner." (PMID 25478796, 2014). "Additionally, STAT1 functions as an oncogenic promoter in leukemia progression." (PMID 38273387, 2024). "However, caspase-6 can cleave STAT1 to inhibit tumor cells in leukemia." (PMID 36675746, 2022). "In addition, STAT1 can act as a potent tumor promoter of leukemia development." (PMID 34506539, 2021). "Furthermore, upon leukemia progression the STAT1 null cells acquired an increased amount of MHC-I." (PMID 32641473, 2020). "Since leukemia cells are very sensitive to HDACi, in contrast to many cells derived from solid tumors, the cell type and perhaps the cellular context may determine the activation of distinct caspases and the impact on STAT1 signaling." (PMID 24810717, 2014). "In leukemias this STAT1 serine site is also critical as natural killer (NK) cells lacking phosphorylation on STAT1 serine 727 displayed enhanced cytotoxicity and were capable to eradicate leukemic cells significantly better when compared to wild-type STAT1-expressing cells." (PMID 25333255, 2014). "At the cellular level, SFX-01 induced STAT1 phosphorylation, suppressed cyclin D1 expression and promoted PKR activation, collectively leading to growth arrest in leukocytes and Shp2-mutant leukemia cell lines." (PMID 40640547, 2025). "In this study, we explored the relative expression levels of key transcription factors in leukemia cells by RT-qPCR, and the results showed that MYC, RXRB, were significantly up-regulated, while STAT1 expression was down-regulated in HAP1 compared to HS-5." (PMID 39465162, 2024). "STAT1 and STAT3 activation is important for the terminal differentiation of immature leukemia cells." (PMID 31117333, 2019). "Since STAT1 expression was elevated in STAT3β-deficient leukemia cells along with IFN-inducible genes, we postulate that the enhanced IFN signaling results from an imbalance in STAT1/3 signaling due to the absence of STAT3β." (PMID 38806478, 2024). "The role of STAT1, STAT3, and STAT5 in leukemia development was confirmed in 1995." (PMID 38273387, 2024). "Furthermore, the ChIP-seq read counts of CEBPB in the peak regions of STAT1 are correlated (with r > 0.3) in lymphoblastoid (GM12878) and in leukemia (K562) cell lines." (PMID 30142147, 2018). "To investigate if blocking Stat1 phosphorylation could modulate beige adipocyte development, we administered one dose of the Stat1 inhibitor, fludarabine, an FDA approved drug to treat leukemia and lymphoma, for 5 consecutive days to 12-month-old control mice." (PMID 37002214, 2023).
glioblastoma (43 papers, 2012 to 2026). The most malignant astrocytic tumor (WHO grade IV). "In DIPG tissues, the combination was predicted to increase the activation of the Rho GTPases (RHOA) previously implicated in STAT1 activation, contributing to changes in cellular morphology that lead to motility and invasion of glioblastoma cells." (PMID 38319732, 2024). "STAT1, a cytoplasmic transcription factor, exerts significant effects in maintaining cell growth and migration in glioblastoma." (PMID 40607003, 2025). "Reduction of STAT1 in glioblastoma cell lines by knock down experiment significantly increased PDCD4 expression and decreased PDCD4 targets in Glioblastoma cell lines." (PMID 37476290, 2023). "Knock down of FAT1 in vitro has also resulted in the reduced expression of STAT1 protein in glioblastoma cell line signifying positive correlation between FAT1 and STAT1." (PMID 37476290, 2023). "Collectively, these indirect and direct evidences further confirmed that interfering with glioblastoma HA pathway promotes M1 macrophages polarization through STAT1 activation." (PMID 35410993, 2022). "In the TIM of glioblastoma, M1-type microglia exert antitumor immune functions by producing proinflammatory cytokines and transcription signals as well as STAT1." (PMID 36056336, 2022). "In a recent study on glioblastoma, SLFN5 expression was associated with the negative regulation of STAT1-mediated Type I IFN responses and, thus, with the promotion of a malignant phenotype." (PMID 34571733, 2021). "Overexpression of STAT1 inhibits proliferation and migration but induces apoptosis in glioblastoma cells." (PMID 29270670, 2018). "Although PCR data does not show si-HEY1 to have a significant effect on STAT1, previous research indicates the overexpression of STAT1 is unique to glioblastoma samples when compared to normal brain tissue samples." (PMID 28574840, 2017). "Taken together, our data suggest that miR203 acts as a tumor suppressor in glioblastoma by suppressing the pro-tumorigenic action of STAT1." (PMID 27705947, 2016). "Mechanistically, we found that enforced miR203 expression in glioblastoma suppressed STAT1 expression directly, as well as that of a number of STAT1 regulated genes." (PMID 27705947, 2016). "MiR203 is underexpressed, while STAT1 is overexpressed in glioblastoma patients, thereby promoting tumorigenesis." (PMID 27705947, 2016). "Gene expression profile analysis performed on murine xenograft models of glioblastoma showed increased transcriptional levels of STAT1/IRF1 signaling in bevacizumab resistant tumors compared to control tumors." (PMID 26362401, 2015). "Some reports also have demonstrated that constitutive STAT1 signaling promotes tumor growth, increases resistance to chemotherapy and radiation, and carries a worse clinical outcome in patients with glioblastoma multiforme." (PMID 25355139, 2014). "In terms of mechanism, STAT1 may mediate epithelial-mesenchymal transition through the wnt/β-catenin signalling pathway to increase glioblastoma growth and migration." (PMID 37837543, 2023). "The increased expression of SIRPα in macrophages could subsequently result in enhanced STAT1 phosphorylation and positively affect M1 macrophages polarization, the induced M1 macrophages contribute to the phagocytosis of glioblastoma cells." (PMID 35410993, 2022). "On balance, it appears to be that the net effect of STAT1 signaling in glioblastoma is context dependent, and this axis may therefore be difficult to therapeutically modulate in a predictable fashion." (PMID 33498872, 2021). "A glioblastoma study identified SLFN5 as a regulator of STAT1 induction by type I IFNs." (PMID 33329603, 2020). "Indeed, STAT1 had been reported to be aberrantly expressed in glioblastoma and an overexpression of STAT1 predicted poor prognosis." (PMID 31803233, 2019).
glioblastoma (continued). "For instance, the dual-specific phosphatase (DUPS4), which is involved in blocking the activation of the extracellular regulated MAP kinase, has previously been shown to interact functionally with STAT1 in mediating sensitivity to erlotinib in human glioblastoma multiforme cell lines." (PMID 30002654, 2018). "Knockdown of STAT1 expression mimicked the effect of overexpression of miR203 in glioblastoma cell lines, and inhibited cell proliferation and migration, increased sensitivity to apoptosis induced by IFN or temozolomide in vitro, and inhibited glioblastoma tumorigenesis in vivo." (PMID 27705947, 2016). "A pro‐GBM mechanism in which CYP2E1‐PPARγ‐STAT‐1/NF‐κB/STAT‐3/STAT‐6 axis fueled tumorigenesis by reprogramming M/Mφ and a newly developed CYP2E1 inhibitor, Q11, as a promising anti‐inflammatory agent for glioblastoma treatment is uncovered." (PMID 37283464, 2023). "However, macrophages are not entirely controlled by glioblastoma cells, and upregulated expression of SIPRα enhances M1 macrophages polarization through activation of STAT1 phosphorylation via an underlying protective mechanism." (PMID 35410993, 2022). "In glioblastoma, PUS7 targets the tRNA for pseudouridylation, affecting the interferon-STAT1 pathway and cell growth by reducing Tyk2 translation." (PMID 41554761, 2026). "To further verify this observation, we infected human glioblastoma cell line SF268 with ZIKV for various intervals and examined the protein expression of STAT1." (PMID 38018976, 2024). "Among the candidate miRNAs, miR-221 has been shown to regulate the expression levels of STAT1 and STAT2 in glioblastoma cells." (PMID 37864270, 2023). "SLFN5 also negatively controls STAT1-mediated transcriptional activation of IFN-stimulated genes and ZEB1 transcription, suppressing the antitumor immune response in glioblastoma cells and the mesenchymal-epithelial transition." (PMID 35768579, 2022). "We transfected U-87 MG cells, a human glioblastoma cell line lacking endogenous α receptor expression with a luciferase reporter responsive to STAT transcription factors (STAT1, STAT3, STAT5), a classical readout of PDGF receptor activity." (PMID 38532028, 2024). "Collectively, these observations indicated that interfering with the HA pathway could promote M1 macrophages polarization via activation of STAT1 phosphorylation and inhibited M2 macrophages polarization via impairment of STAT3 phosphorylation in glioblastoma." (PMID 35410993, 2022). "The basis of such an observation is not clear, however it is of interest that IFNγ-induced STAT1 activation has been previously shown to negatively regulate hypoxia-inducible factor-1 (HIF-1) α-dependent transcription in human glioblastoma cells lines." (PMID 27769057, 2016). "Mechanistically, abnormal HA accumulation could bind to CD44 receptor on macrophages surface, which could regulate downstream STAT1 and STAT3 pathways in macrophages, further leading to the glioblastoma immunosuppressive microenvironment formation and ultimately promoting glioblastoma progression." (PMID 35410993, 2022). "In this study, our results revealed that interfering with HA synthesis in glioblastoma or inhibiting the binding of HA to CD44 on macrophages inhibits M2 macrophages polarization and activates M1 macrophages polarization by regulating STAT3 and STAT1 phosphorylation." (PMID 35410993, 2022). "Work by other authors has reported an SLFN5 co-repressor action with STAT1 in IFN-mediated responses, by promoting malignant progression in glioblastoma, but a direct transcriptional role has not been yet reported." (PMID 32488136, 2020).